GFAP (glial fibrillary acidic protein)
Diseases named in the same sentence as GFAP in open-access papers (continued):
Sharing a sentence is not in itself a finding about the gene and the disease.
infection (continued). "After an injury or infection, GFAP is upregulated, which indicates an astrocyte’s reactivity." (PMID 39203555, 2024). "A secondary band was observed in both the untreated and relapsed infection groups at approximately 80 kDa, indicating that altered GFAP protein structure might be a feature of DCD pathology." (PMID 38782898, 2024). "Astrocytes become reactive in response to central nervous system injury, including infection, trauma, ischemia, and neurodegenerative diseases, with changes in molecular expression and morphology characterized by hypertrophy and increased GFAP expression (mesenchymal filaments)." (PMID 37635786, 2023). "Interestingly, our results showed that the intensity of GFAP fluorescent decreased in the young unvaccinated infected groups, possibly due to the infection of astrocytes by neurotropic influenza viruses, which has been previously reported to lead to apoptosis." (PMID 37063291, 2023). "GAGi.Nef- infection showed a higher level of GFAP mRNA than GAGi infection." (PMID 36818564, 2023). "Likewise, the numbers Iba-1+ microglia of GFAP+ astrocytes within the mPFC were unaffected by infection." (PMID 37596606, 2023). "By using reverse transcription polymerase chain reaction (RT-PCR), we observed the down-regulation of neurotrophin brain-derived neurotrophic factor (BDNF), glial fibrillary acidic protein (GFAP), and hemagglutinin (HA) in mouse lung during the infection (21 days) of IAV." (PMID 38005876, 2023). "However, in our double immunofluorescent staining, the percentage of IL-6+GFAP+ cell was lower than IL-6+Iba1+ cell post-infection, which indicate that the pro-inflammatory cytokine, such as IL-6, was mainly derived from microglia." (PMID 37256871, 2023). "As before, there was robust infection in GFAP+ astrocytes in virally exposed samples after 72 h." (PMID 35858406, 2022). "Strikingly, we observed abundant infection in astrocytes, as indicated by the presence of viral N protein, S RNA, and dsRNA, with 90% of infected cells expressing glial fibrillary acidic protein (GFAP) or Aquaporin 4 (AQP4) throughout the outer subventricular zone (SVZ) of primary cortical tissue." (PMID 35858406, 2022). "Upon a flaviviral infection, highly activated astrocytes increase their production of GFAP, which, combined with the release of inflammatory cytokines and chemokines by other components of the CNS, can lead to a severe course of the disease with a higher fatality rate." (PMID 34307520, 2021). "At 3–4 weeks following infection of the adult retina by GFAP-Math5-Brn3b-tdTomato AAVs, numerous tdTomato-immunoreactive RGCs were observed on the vitreous surface of the retina, which extended axons that were fasciculated into many thick axon bundles immunoreactive for Tuj1." (PMID 34671605, 2021). "Blood-based biomarkers for CNS injury, like neurofilament light chain protein (NfL) and Glial fibrillary acidic protein (GFAp), may be valuable tools for detection and monitoring manifestation during the acute phase of this infection." (PMID 33743046, 2021). "In line with previous observations, this neural culture displayed higher levels of neuronal marker MAP2, compared with glial marker GFAP, and can be infected all lyssavirus strains, with high levels of viral RNA and protein detectable 72 hours post-infection (h.p.i)." (PMID 35004351, 2021). "Notably, besides accumulation of RABV P in NeuN-positive neurons, P also accumulated at GFAP-positive filaments (white arrows), indicating a robust infection of astrocytes by field virus rRABV Fox." (PMID 32053954, 2020). "Sema4D co-localised with HSCs marker (GFAP) revealed that Sema4D in HSCs was significantly increased in mice livers after infection with S. japonicum and could be reduced by treated with HBAAV2/9-Sja-miR-71a (arrows)." (PMID 32944173, 2020).
infection (continued). "As the first serum biomarkers (UCH-L1 and GFAP) were recently approved by the FDA, this approach may be proven as a fast screening tool for patients at high-risk of severe infection outcomes prior to the development of neurological symptoms." (PMID 32912226, 2020). "All four viruses resulted in infection of GFAP-positive cells at levels ranging from 4.9% to 6.7%." (PMID 32053954, 2020). "Despite the results, there are a few limitations in the clinical contribution.Especially after trauma, GFAP increases in intermediate filaments in astrocytes withthe development of astrocytosis in the infection or neurodegenerative process andinduction in the signal pathway in the astrocytes." (PMID 32578724, 2020). "We observed a significant increase in expression of GFAP and Iba1 in the infected group 10 weeks after the infection; in comparison, the artesunate-treated group, with treatment started two weeks after the infection, showed a significant reduction of GFAP and Iba1 expression in spinal cord tissue." (PMID 32230725, 2020). "The rather uniform increase of GFAP levels is indicative of a general response to the infection." (PMID 30068357, 2018). "Levels of GFAP in the hippocampal area began to slightly increase, reaching nearly 2.91-, 3.24-, 2.64- and 3.15-fold higher at 10 dpi and 8, 16 and 20 wpi, respectively, in mice with low-dose infection." (PMID 29273062, 2017). "Ten weeks post-22 L infection, we detected astrogliosis by means of vimentin and GFAP expression." (PMID 29126445, 2017). "In the amygdala, infection of GFAP-positive astrocytes was noted surrounding infected neurons." (PMID 26491149, 2016). "Finally, to test if ceftriaxone inhibited the global astrocyte and microglial activation typically seen during infection, brain slices were probed with the microglial marker Iba-1 and antibodies to the astrocyte-specific filamentous protein, GFAP." (PMID 27281462, 2016). "We also observed infection of some local GFAP-expressing astrocytes." (PMID 21625383, 2011). "Interestingly, we observed a higher infection rate in GFAP than β-tubulin positive cells." (PMID 41139159, 2025). "Interestingly, Wnt 3α largely diminished the reactive astrocyte marker GFAP, which might, at least partly, account for the reduced ND1 transduction/expression, since the GFAP promoter was used in the infection process." (PMID 38891029, 2024). "By infecting mice specifically deficient in astrocyte CCL2 production (GFAP-Cre x CCL2fl/fl), we observed significantly decreased immune cell recruitment to the brain and reduced parasite control during chronic, but not acute, infection." (PMID 38206985, 2024). "Therefore, this restricted milieu may amplify Ser/5-HT-promoted astrocyte infection by T. cruzi, which might be favored by the inability of mouse and human cortical astrocytes (GFAP+ cells) to express the inflammasome NPRL3." (PMID 38776344, 2024). "Importantly, we also observe a reduction in GFAP+IL-33+ cells post-infection, and while our genetic studies support a role for oligodendrocyte-derived IL-33 in this setting, our work does not formally rule out a contribution of IL-33 derived from astrocytes in this model." (PMID 37983247, 2023). "In addition, the inflammatory cytokines Interferon-γ (IFN-γ), tumour necrosis factor α (TNF-α), transforming growth factor-β (TGF-β), and Arginase 1 (Arg-1) were significantly upregulated after the TgCtwh3 infection, while glial fibrillary acidic protein (GFAP) was down regulated." (PMID 37651502, 2023). "This close association could either indicate viral proteins in processes that do not contain GFAP, or infection of a different cell type that are closely associated with astroglia." (PMID 35746689, 2022). "While the initial increase in astrocytic GFAP is expected as part of the initial response to CNS infection, what isn’t expected is the significant increase in expression that takes place in the late stage of infection after chronicity has been well established." (PMID 33816350, 2021).
infection (continued). "After 24 h of infection, the cells were fixed and analyzed by confocal laser scanning microscopy using indirect immunofluorescence stainings against RABV nucleoprotein N, neuron marker MAP2 (microtubule-associated protein 2) and astrocyte marker GFAP (glial fibrillary acidic protein)." (PMID 32053954, 2020). "In mice with different infection doses at 20 wpi, the highest GFAP protein level with a 5.43-fold increase was expressed in the hippocampus of mice with low-dose infection, while 3.49- and 3.71-fold increases were shown in in mice with medium- and high-dose infections, respectively." (PMID 29273062, 2017). "However, by day 10 post infection GFAP mRNA expression was significantly lower in the brains of HSV-IL-2-infected and macrophage-depleted mice compared with parental virus, while its expression in the spinal cords of all group was similar but lower than on day 5 PI." (PMID 28542613, 2017). "Our findings support those reported for experimental neonatal acquired hydrocephalus and also show that congenital and late-onset hydrocephalus, the latter associated with neonatal and postnatal infections, do not present with raised GFAP but that PHH and SB/HC neonates do." (PMID 24351234, 2013). "In our study, we examined GFAP (glial fibrillary acidic protein) immunoreactivity in the hippocampal regions CA1, CA3, and DG to assess astrocytic activation in response to maternal H1N1pdm09 infection." (PMID 41567998, 2025). "We assessed the effect of infection and IFN-β or IFN-λ2/3 neutralization on PD-L1, GFAP (glial and activation marker) and CD11b (macrophage and microglial marker) expression in the mouse retina, using confocal microscopy." (PMID 40599769, 2025). "Conversely, infection-induced upregulation of CXCL10, STEAP4, C3 and GFAP was significantly reduced in CK2βVas-/- mice." (PMID 40929057, 2025). "Although subject to further investigation, additional stainings for the neuronal marker MAP2 and the astrocyte marker GFAP indicate that the morphology and/or integrity of both NSPH cell types is severely affected following infection with VZVORF65-tdT-66." (PMID 39351233, 2024). "The positive cell rates of GFAP and IBA-1 in the 2dpi and 4dpi groups after infection significantly increased compared to their respective control groups." (PMID 39239635, 2024). "On the other hand, infection with HIV-1CH040 demonstrated more prominent effects on neuroinflammation, assessed by an increase in GFAP signal and/or an increase in number of Iba-1+ microglia, across CNS regions." (PMID 38945996, 2024). "Using transfection or infection of VSVG-pseudotyped HIV viruses, we showed that Nef expression down-modulated glial fibrillary acidic protein (GFAP) expression." (PMID 36818564, 2023). "6-week-old mice of the GFAP:GP, aCD20-GFAP:GP, and STOP:GP conditions were treated with TAM (6 weeks post-infection) and sacrificed seven days after initial TAM administration, while mice of MOG:GP were sacrificed 47 days after initial infection." (PMID 36695896, 2023). "Glial fibrillary acidic protein (GFAP) staining, which marks astrocytes, sharply colocalized with spike staining, suggesting that SARS-CoV-2 targets astrocyte infection in these brain organoids." (PMID 36314791, 2022). "The results show that only GFAP could be co-localized with cleaved caspase-3 and that the co-localization between GFAP and cleaved caspase-3 was elevated during AC infection, indicating that astrocytes were the main cell type undergoing apoptosis in mouse brains after infection with AC." (PMID 33683530, 2022). "To further evaluate CNS damage, we detected GFAP and cl-Caspase-3 expression in the brains and found CVA6 infection led to activation of astrocytes and apoptosis of brain cells." (PMID 36036059, 2022). "We assessed the levels of astrocyte (GFAP) and microglial (IBA-1) markers 24 h post-infection to observe the activation of glial cells in the brains of rats in each group." (PMID 34727939, 2021).
infection (continued). "Quantified data found that 99% of GFAP::GFP infected cells were GFAP+ astrocytes, but 52.6% of NeuroD1-GFP infected cells already became NeuN+ within 1 month of infection." (PMID 33224952, 2020). "Activation of astrocytes in response to SVNI infection was shown in culture, and an in vivo study demonstrated an increase in Gfap promoter activity in SVNI GFAP-luciferase mice." (PMID 32831144, 2020). "In this report, we demonstrate that GFAP expression was significantly affected by HSV-IL-2 infection or after depletion of macrophages and infection with WT HSV-1." (PMID 28542613, 2017). "We were unable to detect any significant differences in GFAP or HOPX staining between GFP and NFIX infections." (PMID 24848099, 2014). "With a combination of ISH for VP1 and IC, the cellular loci of infection for the TMEV were revealed to include Iba+ infiltrating macrophage/microglial cells, GFAP+ astrocytes, NeuN+ neurons and CAII+ oligodendrocytes." (PMID 19094215, 2008). "In addition to microglia/macrophage number and activation, the GFAP-positive area was determined to investigate the influence of GM1 lysosomal storage and TMEV infection on astrocytes in the brain of C57BL/6 mice." (PMID 40270964, 2025). "An interesting discrepancy, however, was the increase in GFAP for both HPeV-1 and HPeV-3 infection in co-cultures, while in neural organoids, we did not observe upregulation of GFAP in our proteomics data." (PMID 41191104, 2025). "We speculate that this infection may have triggered an immune response, resulting in the patient’s positive MOG and GFAP antibodie." (PMID 41333477, 2025). "PKH67 labeled EVs colocalized in GFAP+ astrocyte cultures independent of the infection conditions of the neurons from which they were derived." (PMID 40523037, 2025). "Interestingly, astrocytic GFAP astrogliosis was most pronounced in the frontal cortex and hippocampus in HIV-infected mice analyzed at 2-weeks post-infection." (PMID 38945996, 2024). "Before the infection with HSV-1, COs were characterized by IHC for brain cell types including neurons, microglia, astrocytes, and oligodendrocytes using MAP2/TUJ-1-, IBA1-, GFAP-, and Olig2-specific antibodies, respectively." (PMID 39176174, 2024). "MCMV infection induced the strong up-regulation of GFAP on astrocytes in the GCL and disrupted their normal patterning across all time points, suggesting that reactive astrocytes were induced early in the infection and sustained throughout the time course." (PMID 39565860, 2024). "On day14 post-infection, immunostaining with astrocytic (GFAP) or neuronal (MAP2 and TUJ1) markers showed that NeuroD1-infected cells displayed decreased GFAP signal (91.6 ± 2.5% → 48.3 ± 1.4%) and exhibited neuronal morphology in both GFAP + and GFAP − cells." (PMID 39014391, 2024). "Compared to brains of mock-infected mice, the brains of ZIKV-infected adult mice showed increased immunostaining of glial fibrillary acidic protein (GFAP) in the proximity of lesions and in the CA1 and dentate gyrus hippocampal regions (Fig. EV1A) at 12 days post infection (dpi)." (PMID 39009885, 2024). "In contrast to microglia, where more microglia were expressing FasL than Fas, astrocytes (GFAP+) showed an increase in Fas, rather than FasL expression both at 5 and 9 days post-infection." (PMID 39339840, 2024). "Despite the shared histopathological characteristics, such as cytoskeletal hypertrophy and GFAP upregulation, astrocytes activated by compression, infection or hyperexcitation failed to initiate a proliferative program." (PMID 38066208, 2023). "While total GFAP+ astrocyte numbers were stable, IL-33+ mature-myelinating oligodendrocyte cell numbers (MBP+IL-33+) and overall MBP staining were decreased post-infection." (PMID 37983247, 2023). "Littermate Stop-GPflox/+ mice, termed STOP:GP, served as post-infection controls as they lack the GFAP-CreERT2tg/+ and therefore do not express the full-length LCMV GP upon TAM administration." (PMID 36695896, 2023).
infection (continued). "Activation of astrocytes is expected to occur in the presence of WNV, and this was observed in the BSCs following WNV infection because GFAP, VIM, LCN2, and STEAP4 all showed enhanced expression following infection with WNV compared with the mock-infected samples." (PMID 35412380, 2022). "At week 16, we observed infection of a few GFAP+ cells in one stem cell line, but infection was absent in a second stem cell line at the same timepoint." (PMID 35858406, 2022). "The number of astrocytes (by expression of GFAP), microglial (by Iba1), and neuronal cells (by MAP-2) in the brain following IM and IC inoculations of SRV were evaluated by immunohistochemistry and H & E staining 7 to 30 days post-infection." (PMID 34712425, 2021). "By 3.5 days post-infection with the GFAP-Math5-Brn3b-tdTomato AAVs, no tdTomato+ axons were seen in the optic nerve, in agreement with the observation that there were no RGCs reprogrammed from MG by this time." (PMID 34671605, 2021). "Twenty-four hours following infection with either Asian (Rio-U1) or African (MR766) lineage ZIKV, cultured astrocytes (GFAP+) from infant macaques were co-positive for the viral antigens envelope (E) and nonstructural protein 3 (NS3), indicating permissiveness to infection." (PMID 33405202, 2021). "Here, we show that after adjusting for sex and infection, lower BE and higher lactate (biochemical markers of decreased perfusion), and worse Sarnat scores (functional outcome) all relate to lower VEGF and higher tau, GFAP, and IL-10." (PMID 34795631, 2021). "Different from A1 astrocyte genes, the A2 reactive astrocyte genes were not changed despite a decrease of GFAP expression after NeuroD1-infection." (PMID 33250718, 2020). "We observed increased expression of IBA-1 (P < 0.05), CD 11B (P < 0.05), and GFAP (P < 0.05) 10 days after infection, with no significant changes in Oligo or NeuN levels in either the PFC or the hippocampus." (PMID 31901235, 2020). "Although free from infection, 10-day group rats exhibited increased expression levels of cytokines and markers of oxidative stress, microglial activation (IBA-1), and astrocyte activation (GFAP) similar to those seen in the 24-h group." (PMID 31901235, 2020). "Although GFAP expression did not change significantly during the course of infection, expression was highest in the brainstem and associated with SIV RNA expression." (PMID 32669339, 2020). "L. amazonensis induced a moderate astrogliosis at the 30th day of infection as observed by increase of GFAP expression, hypertrophy, and no pronounced overlapping of astrocyte processes." (PMID 31138231, 2019). "In contrast, no significant change of astrocyte marker GFAP (glial fibrillary acidic protein) was observed in RV-∆G and rAAV2-retro infection both at the injection sites and in retrogradely labeled nuclei." (PMID 30736827, 2019). "Infected mice presented an increase of GFAP intensity of fluorescence in both gray and white matter areas of the ipsilateral side of the infection in the spinal cord compared to non-infected mice." (PMID 31138231, 2019). "At 3 days post-infection, mock- and VZV-infected qHA-sps and qHA-hps were examined for morphological changes by immunofluorescence antibody assay using antibodies directed against glial fibrillary acidic protein and VZV." (PMID 30442152, 2018). "The percentage area staining for GFAP-positive cells was not statistically different between all the control and infection groups." (PMID 29980196, 2018). "Meanwhile, we also found significant increases in GFAP in the mice hippocampus, beginning early at 10 dpi, remaining stable and high until 20 wpi, irrespective of the inoculum level or infection time." (PMID 29273062, 2017). "We propose that suppression of GFAP on astrocytes in the absence of macrophages or in the presence of IL-2 following infection with HSV-1 affect IL-12p70 expression thus leading to autoreactivity of T cells and thus CNS demyelination." (PMID 28542613, 2017).